CSF1 (colony stimulating factor 1)
Diseases named in the same sentence as CSF1 in open-access papers (continued):
Sharing a sentence is not in itself a finding about the gene and the disease.
tumor (continued). "Tumor cell derived inflammatory cytokines and growth factors including colony stimulating factor (CSF-1), GM-CSF, CCL2 and other factors which participate in tumor progression." (PMID 29137220, 2017). "In a preclinical tumor model, ADT also enhances the expression of macrophage-recruiting chemokine CSF1 and M2-promoting cytokines, such as IL13 and IL10 in PCa cells, resulting in more macrophage infiltration and expression of MMP9 and VEGF46." (PMID 29142311, 2017). "Chemokines and cytokines including CCL2, CXCL12, CSF1, CCL5, CCL22, IL6 and TGFB3 are secreted by primary tumor cells to recruit immune cells to escape from anti-tumor immune responses." (PMID 28591712, 2017). "Local signals in the tumor microenvironment (IL-4, IL-6, IL-10, PGE2, CSF-1, and transforming growth factor-β, TGF-β) polarize macrophages into alternative, protumoral M2-like cells." (PMID 28197019, 2017). "Monocyte infiltration into a tumor is mediated by chemokines (e.g., CCL2, CCL5, and CXCL12), CSF-1, and components of the complement cascade." (PMID 26980947, 2016). "In inflammatory cells, the NFκB pathway results in the induction of numerous tumor-promoting chemokines and cytokines such as IL-6, TNF-α, IL-1β, CXCL8, VEGF, and CSF-1." (PMID 26980947, 2016). "The mRNA levels of colorectal inflammatory cytokines TNF-α, IL-1β, IL-6, CSF-1, and MCP-1, and COX-2 were increased in tumor and surrounding tissues from AOM/DSS-treated mice." (PMID 27557503, 2016). "It is well known that a positive feedback loop exists between TAMs and tumor cells, involving epidermal growth factor (EGF) and CSF-1." (PMID 26980947, 2016). "Our data showed that treatment with embelin led to a significant impairment in the expression of CSF1, CCL2 and GM-CSF in tumor tissues whereas only very mild apoptosis in macrophages was detected." (PMID 26799669, 2016). "CSF1 and CSF1R have been reported to be expressed by the tumor epithelium in several human epithelial cancers, including breast, ovarian, lung, endometrial, trophoblastic and prostatic cancer." (PMID 27107415, 2016). "CSF-1 receptor (CSF-1R) signaling is currently under investigation as a therapeutic target and we have identified CSF-1-stimulated macrophage motility, through PI3K p110δ and SFKs, as a promising specific target to prevent tumor invasion." (PMID 31453214, 2016). "TAMs refers to macrophages in the tumor microenvironment which come from monocytes and can be attracted to the tumor tissue by chemotactic factors including VEGF, CSF-1, GM-CSF and so on27." (PMID 26831282, 2016). "The production of colony stimulating factor 1 (CSF-1) in tumors recruits myeloid cells such as M2-polarized macrophages and myeloid derived suppressor cells (MDSC), leading to an immune suppressive tumor milieu." (PMID 25939769, 2015). "Expression of both CSF-1 and CCL2 have been independently correlated with cancer progression in several tumour types." (PMID 26174804, 2015). "Numerous cancers express tumor-derived factors, such as CSF-1 and CCL2, to recruit monocytes and promote their differentiation to macrophages in the tumor microenvironment." (PMID 26231039, 2015). "Experimental models suggest that cancer cells release factors such as CSF-1, which stimulate macrophages in the tumor microenvironment and release EGF promoting tumor proliferation." (PMID 24879524, 2014). "Following tumor irradiation, DNA damage, cell death, and increased tumor hypoxia promotes the production of VEGF, SDF-1, and CSF-1 resulting in the recruitment, infiltration, and retention of monocytes/macrophages within tumors." (PMID 23882218, 2013). "Expression of chemokine for monocytes (CSF-1 and CCL-2) were low in tumor cells from EGCG-treated mice, and cytokines of TAM was skewed from M2- into M1-like phenotype by EGCG as evidenced by decreased IL-6 and TGF-β and increased TNF-α." (PMID 24044575, 2013).
tumor (continued). "Tumor cells, among other cytokines, produce MCP-1 and colony stimulating factor-1 (CSF-1) which participates in mobilization of TAM-progenitors from the bone marrow and homing to tumor stroma." (PMID 23898462, 2013). "We next measured the levels of CSF-1 and CCL-2, major chemokines involved in the monocyte recruitment into tumor microenvironment, in tumor cells isolated from mice by RT-qPCR." (PMID 24044575, 2013). "The CSF-1 blockade reduced TAM recruitment and angiogenesis, as well as down-regulated MMP-2 and MMP-12 expression in the tumor." (PMID 24314323, 2013). "Macrophages express CSF-1 receptors and produce EGF, whereas tumour cells express EGF receptors and produce CSF-1." (PMID 22005011, 2011). "Tumour cells produce IL-1-6-8-11, PgE2, TGFα, TGFβ, EGF, VEGF, TNF, CSF-1, GM-CSF, and M-CSF, which can directly or indirectly stimulate osteoclastic activity and then bone resorption." (PMID 22312491, 2011). "Since CSF1-activating translocation-driven macrophage recruitment is fundamental to the pathophysiology of PVNS, this neoplasm plausibly represents an index disease model for assessing the value of anti-CSF1 therapeutics." (PMID 20981142, 2010). "Although homing of macrophage to tumors is poorly understood, tumor cells are known to release macrophage chemoattractants including CCL2, CCL5, CCL7, CCL8, CXCL12, VEGF and CSF-1." (PMID 19696929, 2009). "The cytokines most often detected in serum and ascites of patients with EOC include TNFα, IL-10, IL-6, CSF1 (MCSF), IL-1, and TGFβ isotypes, all of which can be produced by activated MA or by the tumor cells." (PMID 16824216, 2006). "Similarly, removal of CSF-1 from transplanted tumours also resulted in an impairment of growth with extensive necrosis and poor vascularisation, phenotypes that could be reversed by treatment of the mice with CSF-1." (PMID 15164120, 2004). "Finally, in a mouse metastasis model, blocking the CSF1/CSF1R axis with a CSF1R inhibitor reduced the M2-like TAMs recruitment and CRC tumor metastasis burden." (PMID 41639044, 2026). "Previous evidence reveals that circulating monocytes are chemoattracted to tumor cells and differentiated into TAMs by several stimuli including IL-6, IL-10, VEGF, macrophage colony stimulating factor (M-CSF, also known as CSF-1), TGF-β, GM-CSF, and chemokines." (PMID 40050933, 2025). "CSF1 upregulation stimulates the proliferation of neoplastic cells within the tumor and the recruitment of non-neoplastic macrophages that express the CSF1 receptor (CSF1R) to the synovium." (PMID 40392406, 2025). "Pexidartinib, a CSF1 receptor inhibitor, is approved by the FDA for the treatment of adult patients with tenosynovial giant cell tumor, which is a rare and locally aggressive nonmalignant tumor that overexpresses CSF-1." (PMID 39941714, 2025). "TREM2 is expressed on CSF1R+ TAMs and modulated by CSF1, suggesting that dual inhibition of CSF1R and TREM2 may further potentiate macrophage repolarization and tumor immune surveillance." (PMID 40330466, 2025). "In each tumor component, the prognostic impact of CD163 and CSF-1 was examined." (PMID 39488822, 2025). "Mechanistically, SPON2 enhances interleukin 10 (IL10), C-C motif chemokine ligand 2 (CCL2), and colony stimulating factor 1 (CSF1) secretion, drives M2 macrophage polarization, and activates the NF-κB/VEGF signaling axis to facilitate EMT and tumor progression." (PMID 40730813, 2025). "Notably, upregulation of immunosuppressive pathways such as the CSF1 axis, driven by MORF4L2, enhances M2 polarization and suppresses anti-tumor immunity." (PMID 41310829, 2025). "Thus, by targeting the CSF-1/CSF-1R axis to modulate NKG2D ligand expression, providing a potential strategy for tumor immunotherapy." (PMID 41301424, 2025).
tumor (continued). "After EMT induction and stromal reorganization, tumor cells proceed to intravasate into blood vessels, a step facilitated by a paracrine signaling loop involving tumor-derived CSF1 and macrophage-secreted EGF that directs tumor cell migration toward vasculature." (PMID 41417432, 2025). "In TME, as a source of immunosuppressive cytokines and pro-tumor growth factors, tumor-associated macrophages (TAMs) are infiltrated and activated to express CSF1 and chemokine (C-C motif) ligand 2 (CCL2), thereby promoting tumor cell infiltration and metastasis." (PMID 40191727, 2025). "We found that unlike tumor cells expressing CSF-1, tumor cells with reduced CSF-1 expression did not support increased trans-endothelial migration in the presence of macrophages." (PMID 40646332, 2025). "Biologically, an elevated monocyte burden reflects enhanced recruitment of circulating monocytes into the tumor microenvironment, where they differentiate into TAMs under the influence of cytokines such as IL-6, transforming growth factor-β (TGF-β), and colony-stimulating factor-1 (CSF-1)." (PMID 41487591, 2025). "CSF-1 plays a critical role in TAM activation and their transition to an pro-tumor phenotype." (PMID 40845580, 2025). "Tumor-associated macrophages (TAMs) derived from blood monocytes, myeloid-derived suppressor cells, and tissue resident macrophages are induced and differentiated in tumor tissues by cytokines such as C-C motif chemokine ligand 2 (CCL2), CCL5, and colony-stimulating factor 1 (CSF-1)." (PMID 41002446, 2025). "Because CSF1/CSF1R signalling drives PVNS and targeted inhibitors such as vimseltinib achieve significant tumour regression and functional improvement, similar targeted approaches might be explored for diffuse synovial proliferative disorders." (PMID 41409756, 2025). "Our study mainly addresses the overall macrophage changes driven by increased CSF1 secretion from hybrids and their influence on tumor progression, without delving into a detailed characterization of macrophage subtypes." (PMID 40287444, 2025). "Despite the promising preclinical studies using CSF-1/CSF-1R inhibitors in combination with chemotherapy, immunotherapy, or radiotherapy, phase II clinical trials have not yielded the same anti-tumor efficacies." (PMID 40646332, 2025). "Blocking various chemokines produced by tumor and stromal cells, such as monocyte chemoattractant protein-1 (MCP-1), prostaglandin E2 (PGE2), colony-stimulating factor 1, and CCN3, can inhibit the recruitment of TAMs to tumor sites, thereby suppressing tumor progression and preventing metastasis." (PMID 40304000, 2025). "Furthermore, tumor-derived CSF-1 interacts with epidermal growth factor (EGF) signaling in macrophages, promoting their perivascular accumulation and enabling immune evasion by tumor cells." (PMID 40936918, 2025). "The upregulation of VEGF expression by TAM is mediated by CSF-1 and hypoxia-inducing factor (HIF), and is further enhanced in the hypoxic tumor microenvironment, where VEGF attracts monocytes through VEGF receptor (flt-1), thus creating a positive feedback loop of tumor vascularization." (PMID 39606239, 2024). "Colony-stimulating factor 1 (CSF1) secreted by HCC cells promotes overexpression of allograft inflammatory factor 1 (AIF1) in macrophages and induces a transformation of macrophages into the M2 phenotype, resulting in enhanced migration of tumor cells." (PMID 38957393, 2024). "Recent studies indicate that signaling through CSF-1/1R within tumors may enhance TAM2’s recruitment and foster an anti-inflammatory environment, ultimately aiding in tumor progression and metastasis." (PMID 39457618, 2024). "Chemoattractants, produced by malignant cells and the stromal tumor compartment, such as C-C Motif Chemokine Ligand 2 (CCL2), vascular endothelial growth factor (VEGF), CXCL12 (SDF1) and colony-stimulating factor-1 (CSF-1), recruit monocytes from the bloodstream that migrate into tumor site." (PMID 38397187, 2024).
tumor (continued). "By paracrine signaling loops involving CSF-1 from the tumor and EGF from macrophages, TAMs may encourage tumor cell invasion." (PMID 38326735, 2024). "Pexidartinib (PLX3397), a CSF1/CSF1R-signaling inhibitor, could induce a reduction in the number of TAMs and lead to a remarkable delay in tumor recurrence." (PMID 39065562, 2024). "Furthermore, tumor-produced factors including IL-6, TGF-β and CSF-1 can also induce the polarization of TAM towards the M2 phenotype." (PMID 39606239, 2024). "However, the expression of molecules such as interleukin-4 (IL-4), colony-stimulating factor 1 (CSF-1) and arginnse-1 (Arg-1) in the TME are increased with the development of tumor, which induce the transformation of M1-type TAMs into M2-type TAMs." (PMID 38970071, 2024). "For example, TAMs release CSF-1 and CXCL1 helping tumor migration and EMT." (PMID 39104525, 2024). "HIF signaling in tumor cells triggers the expression of the CCL-5 (C-C motif ligand 5) chemokine and M-CSF1 (macrophage colony stimulating factor 1) cytokine, attracting macrophages and mesenchymal stem cells to the tumor microenvironment, thereby promoting cell invasion, migration and metastasis." (PMID 38791951, 2024). "We also suggest CAFs secreted CSF1 or FN1 could unidirectionally target cDC2, C1QC+TAMs, and SPP1+TAMs to promote macrophage or cDCs differentiation, as well as tumor development." (PMID 39323622, 2024). "In most cancers, macrophages are enriched by infiltrating MDMs that are recruited from the periphery in response to signals from the TME (e.g., CCL2, CCL9, CSF-1, VEGF, and TGF-b), and their in situ phenotype is shaped by a combination of organ- and tumor-derived signals." (PMID 39068459, 2024). "While blockade of the CSF1/CSF1R pathway has shown promise in reducing immunosuppressive M2-like macrophages, recent clinical trials have yielded disappointing outcomes, emphasizing the significance of treatment timing and tumor type." (PMID 38517331, 2024). "Studies showed that activation of YAP is an important step in TAM recruitment towards TME in HCC via modulating the levels of IL-6, CSF-1 and CCL-2 secreted by the tumour cells, thereby inducing the formation of tumour initiation cells and remodelling the composition of TME." (PMID 39320855, 2024). "Interestingly, immunomodulatory proteins such as CSF-1, CCL2, FTH, FTL, and TGF-β chemokines have been identified in tumor exosomes." (PMID 39008536, 2024). "In addition, the CSF-1/CSFR-1 blocker inhibits the recruitment of TAMs into the tumor nest and has anti-tumor effects in clinical models." (PMID 38693304, 2024). "Signaling via the Hippo pathway, including its effectors YAP/TAZ, drives the expression/secretion of numerous cytokines (e.g., IL-4, IL-6, CSF-1) that help recruit monocytes to the TME, followed by their M2-like polarization into TAMs that express tumor immune checkpoints such as PD-1." (PMID 39410029, 2024). "Blockade of CSF1 has been shown to deplete TAM and prevent TAM recruitment to the tumor." (PMID 36742323, 2023). "One of the most well-characterized techniques includes inhibiting colony-stimulating factor 1 (CSF-1) or its receptor, CSF1R, to deplete and/or decrease pro-tumor macrophages, resulting in CSF1R-dependent macrophage infiltration, thereby boosting immune-suppressing TMEs." (PMID 37426676, 2023). "Many inhibitors, such as inhibitors of ANG2 (Trebananib), CCL2/CCR2 (Carlumab and PF-04136309), CCL5/CCR5 (Leronlimab, Maraviroc, and Maraviroc), CSF-1/CSF-1R (Emactuzumab and Pexidartinib), and VEGF have been shown to inhibit macrophage recruitment for tumor growth." (PMID 37211559, 2023). "Although deletion of CSF1 did not change the rate of 4T1 cell proliferation in vitro, we observed a dramatic decrease in the rate of tumor growth in BALB/c mice as compared to the 4T1 parental cell line." (PMID 37505292, 2023).
tumor (continued). "The impact can be reduced by blocking the myeloid cell recruitment to the tumor; for instance, the inhibition of the CSF1/CSF1R myeloid recruitment signature expressed by both myeloid and tumor cells was shown to effectively prevent the recruitment and survival of TAMs in carcinomas." (PMID 38136307, 2023). "Additionally, tumor-derived cytokines, such as CCL2 and CSF1, attract peripheral blood-derived macrophages to tumors and induce their differentiation to the M2 type." (PMID 37275909, 2023). "We also compared TCGA tumor samples to GTEx normal samples to determine whether SPP1 and CSF1 were up- or downregulated in HCC." (PMID 37097499, 2023). "Given the importance of CSF1 in macrophage recruitment to the TME, MYCN-amplified PDX-COJEC was xenografted to a nude mouse model to test the effect of anti-CSF1R treatment on inhibiting macrophage recruitment to NB tumours." (PMID 37887559, 2023). "A negative prognostic value of plasma CSF1/M-CSF was seen in iCCA and GBC, further implicating tumor-associated macrophages and the interplay between inflammatory activity and tumor progression as a possible therapeutic target in BTC." (PMID 37404757, 2023). "Moreover, VEGF production is greatly increased when TAMs are stimulated with CSF-1 or CCL2, inducing increased angiogenesis when these two cytokines/chemokines are present in large amounts within the tumor." (PMID 37143666, 2023). "Currently, there is a gap in knowledge regarding the impact of combining inhibitors of the CSF1/CSF1R signaling axis with cancer vaccines and whether this approach could enhance the anti-tumor responses in the tumor microenvironment of solid tumors." (PMID 37505292, 2023). "In addition, CSF-1 induces MDSC tumor invasion and combines the treatment of anti-CTLA-4 with CSF-1/CSF-1R to inhibit MDSC signaling." (PMID 37892995, 2023). "Large numbers of macrophages extravasate in response to CSF-1 but, since they are not strongly attracted to the tumour mass, they remain in the stroma." (PMID 36972297, 2023). "These phenomena are not due to direct effects of OPN on tumor cells, but rather due to indirect regulatory effects that induce secretion of CSF-1 by macrophages via the PI3K/AKT/NF-κB/p65 pathway." (PMID 37153567, 2023). "In some tumor-related studies, SPP1 and CSF1 exhibit the same expression trend and function." (PMID 37097499, 2023). "Successful immune escape of tumor cells includes also the production of soluble factors in the microenvironment by tumor cells (TGF-β, LDH5), the induction of co-inhibitory molecules (PD-1, LAG-3 and TIM-3) and the release of immunosuppressive factors (CSF-1, VEGF, PGE2, NO, Arg I, IDO and Gal-1)." (PMID 35603195, 2022). "Furthermore, RNA sequencing analysis from TCGA data showed that the expression of NOS3/NOS3 positively correlated with the expression of CSF1, CSF1R, CD163, and several other tumor-promoting immune cell markers in high-grade PCa (Gleason 9)." (PMID 36209194, 2022). "In the CSF1-positive cases, many CSF1-positive cells were scattered in the tumor and discernable cytoplasmic staining was seen regardless of its intensity." (PMID 36320082, 2022). "We then overexpressed CSF-1 in epithelial 4NQO-L cells and evaluated the tumor response to trametinib in vivo, including profiling the number of MDSCs expressing CD11c+ and CD8+ T cells in the tumor." (PMID 35292516, 2022). "The resulting fusion protein is cleaved and leads to uncontrolled CSF1 (colony-stimulating factor 1) secretion by tumor cells, which attracts non-neoplastic cells (ie, macrophages and monocytes) expressing the CSF1 receptor (CSF1R), via a paracrine effect." (PMID 36439507, 2022).